SIRT1 (sirtuin 1)
Diseases named in the same sentence as SIRT1 in open-access papers (continued):
Sharing a sentence is not in itself a finding about the gene and the disease.
steatosis (97 papers, 2011 to 2026). Increased lipid within the cytoplasm of cells. "Activation of SirT1 ameliorates Non-Alcoholic Fatty Liver (NAFL); conversely, hepatic SirT1 deficiency leads to steatosis, and thiol modification of SirT1 regulates lipid metabolism through acetylation of key transcription factors." (PMID 37759983, 2023). "Hepatic miR-34a overexpression was observed in NAFLD, and miR-34a upregulation caused steatosis by downregulating peroxisome proliferator-activated receptor alpha (PPARα) and sirtuin 1 (SIRT1)." (PMID 35052597, 2021). "Previous studies have shown that specific ablation of SIRT1 in liver is associated with rapid onset and progression of steatosis in response to ethanol exposure." (PMID 30794635, 2019). "Deletion of ACE2 causes CD36/sirtuin 1 axis impairment and thereby interferes with lipid homeostasis, leading to lipodystrophy and steatosis." (PMID 28101297, 2016). "Importantly, the downregulation of Jmjd3 and its associated factors (Sirt1, Fgf21, Ppara) in the mouse liver results in reduced hepatic β-oxidation and increased steatosis." (PMID 33193730, 2020). "Therefore, PIAS4 might play a critical role in promoting steatosis-associated fibrogenesis in vivo likely through repressing SIRT1 transcription." (PMID 27323886, 2016). "Studies in aged mice exposed to chronic ethanol show increased steatosis, neutrophil infiltration, and fibrosis, correlating with reduced hepatic SIRT1 levels." (PMID 40052151, 2025). "NMN supplementation likely enhanced the effectiveness of SIRT1 activation, as indicated by decreased lobular inflammation and steatosis." (PMID 40166461, 2025). "By influencing the AMPK pathway and enhancing SIRT1 activity, luteolin also lessens alcohol-induced steatosis and inflammation and slows the progression of alcoholic liver disease." (PMID 40569949, 2025). "In contrast, ethanol-mediated inhibition of SIRT1 disrupts the lipid-1 pathway, leading to steatosis through an altered lipid-1β/α ratio." (PMID 40052151, 2025). "Increased levels of SIRT1 protect mice against hepatic inflammation and steatosis induced by a high‐fat diet (HFD), while its inhibition worsens these conditions." (PMID 38558505, 2024). "In this context, the upregulation of miR-34a results in the downregulation of hepatic PPARα and SIRT1, which results in reduced fatty acid oxidation and the development of steatosis." (PMID 39133714, 2024). "Flavones, isolated from Penthorum chinense, a plant typical from some regions in Asia, had an anti-steatosis potential in a cellular model of steatosis (concentrations ranging from 100 μM to 10 μM) by inhibiting SIRT1/AMPK pathways." (PMID 37755111, 2023). "Here, SalB confers protection against hepatic steatosis and inflammation through SIRT1-mediated HMGB1 deacetylation." (PMID 35873636, 2022). "Neutrophil-specific NCF1 promotes alcohol-induced steatosis by inhibiting hepatic SIRT1 and AMPK activation." (PMID 35838051, 2022). "In another study, ob/ob mice under calorie restriction or metformin treatment showed increased SIRT1 levels and autophagic flux, as well as reduced steatosis in comparison to ad libitum fed animals." (PMID 33937257, 2021). "The similar contributions of SIRT1 activation in different models suggest a common point of intervention in steatosis development and subsequent resolution." (PMID 33937257, 2021). "Similar to miR-21, the inhibition of miR-34a alleviated steatosis by the upregulation of Ppara and sirtuin 1 (Sirt1) expression." (PMID 35052690, 2021). "In vitro and in vivo studies in mice observed that miR-34a specifically targets PPARα and Sirtuin 1 (SIRT1), thereby suppressing FAs catabolism and eliciting steatosis." (PMID 34299336, 2021). "Fucoidan inhibited alcohol-induced steatosis and disorders of bile acid metabolism in mice through the AMPKα1/SIRT1 pathway and the gut microbiota–bile acid–liver axis and protected against alcohol-induced liver injury in vivo." (PMID 33994911, 2021).
steatosis (continued). "Through different pharmacological interventions, i.e., ginsenoside Rb2, erythropoietin, or resveratrol, authors found that AMPK activation and increased levels of SIRT1 both increase autophagic flux and reduce steatosis." (PMID 33937257, 2021). "Resveratrol is defined as a SIRT1 activator and is described by many authors to increase autophagic flux and alleviate steatosis in many rodent models, including HFD, MCD, and genetic interventions thought to relieve ER stress and inflammation." (PMID 33937257, 2021). "The increase in miR-34a has been reported to be responsible for decreasing the expression of SIRT1, resulting in steatosis." (PMID 34884968, 2021). "The present study has confirmed the significant efficacy of OMT for improving steatosis and revealed hepatic proteomic changes and Sirt1/AMPK signaling activation by OMT treatment in rats with steatosis." (PMID 32210812, 2020). "Recent studies indicate that ethanol mediated SIRT1 downregulation promote two key events in the development of steatosis." (PMID 33162823, 2020). "For example, the increased expression of miR-181b in NAFLD acted as a regulator of the steatosis by targeting SIRT1 in the progression of NAFLD." (PMID 32406504, 2020). "OMT significantly decreased the expressions of L-FABP, Plin2, FASN and SCD1 and increased Sirt1 expression and AMPKα phosphorylation in the liver of rats with steatosis." (PMID 32210812, 2020). "Disruption of the signaling network by ethanol via SIRT1 inhibition ultimately leads to steatosis and inflammatory injury in liver." (PMID 33162823, 2020). "Our previous study also demonstrated that troxerutin, a flavonoid, markedly renewed Sirt1 levels to protect mouse liver from HFD-induced steatosis." (PMID 32110174, 2020). "It is reported that SIRT1 was targeted by miR‐181b to regulate steatosis and down‐regulated in NAFLD." (PMID 32324317, 2020). "Our data indicated that OMT significantly increased hepatic expression of Sirt1, which is down-regulated in the liver of steatosis rats." (PMID 32210812, 2020). "Resveratrol (a pharmacological SIRT1 activator) significantly prevented hepatocyte ballooning and steatosis, along with the changed levels of LC3-II, Beclin 1, and P62, as well as ER stress." (PMID 32477116, 2020). "Conversely, the antisense silencing of miR-34a-5p in NAFLD in rodents improved steatosis via over-expression of SIRT1." (PMID 31500354, 2019). "The expression of type IV collagen, SIRT1, and heat shock protein 70 (HSP70), proteins that are associated with steatosis, inflammation, and fibrosis, was analyzed in the livers of rats that drank the HFCS beverage using Western blotting (WB)." (PMID 31315223, 2019). "Growing evidences from both human and experimental studies revealed that impaired SIRT1 signaling is associated with alcoholic liver disease and genetic or pharmacological stimulations of SIRT1 protect against steatosis and/or steatohepatitis." (PMID 29516009, 2018). "Hepatocyte-specific deletion of SIRT1 resulted in hepatic steatosis and inflammation through changing fatty acid metabolism." (PMID 29123480, 2017). "One such treatment is SRT1720, which is a Sirt1 activator previously shown to block steatosis in fasting mice." (PMID 27224926, 2016). "The important finding in the present study was that HCLD feeding induced steatosis potentially by miR-34a/SIRT1 axis." (PMID 26608583, 2015). "Preliminary data generated from our laboratory revealed a novel role of APO10LA in up-regulating hepatic expression of SIRT1, decreasing acetylation of SIRT1 downstream target, and inhibiting steatosis in genetically-induced obese (ob/ob) mice." (PMID 24379011, 2013).
steatosis (continued). "SIRT1 modulates steatosis development through inhibiting the expression of lipogenic transcription factor SREBP-1c, and increasing mitochondrial biogenesis by modulating PGC-1α acetylation." (PMID 24379011, 2013). "Genetic or pharmacological inhibition of SIRT1 abolishes NR-induced mitochondrial improvements and aggravates steatosis, and human alcoholic livers show reduced SIRT1 activity, enhanced PGC-1α acetylation, and lower NRF1/TFAM expression, mirroring these findings." (PMID 41516357, 2026). "What’s more, several studies have demonstrated that SIRT1 play a significant role in the process of inflammation, researchers delete SIRT1 in mouse hepatocytes and find that the liver-specific SIRT1 knockout is easier suffer from hepatic steatosis and hepatic inflammation." (PMID 40567502, 2025). "This treatment showed the key pathogenic features of NAFLD/NASH as enhanced steatosis, characterized by the upregulation of FASN and SCD1 and a concomitant reduction in β-oxidation-related pathways, as evidenced by a decreased expression of SIRT1 and PGC1α." (PMID 40649760, 2025). "To confirm the role of AdipoR1/AMPK/SIRT1 signaling pathway in the improvement of HepG2 cell steatosis by YCLLT, we silenced AdipoR1 to further explore the molecular mechanism of YCLLT, and the results showed that silencing of AdipoR1 inhibited the improvement of YCLLT in NAFLD cell model." (PMID 39807243, 2025). "SIRT1 deficiency triggers the activation of the NF-κB pathway, leading to increased expression of inflammatory factors like IL-1β, IL-6, and TNF-α, accelerating the progression of NAFLD from simple steatosis to steatohepatitis." (PMID 39949396, 2024). "In addition, SIRT1 and PPAR-α, biomarkers associated with steatosis development, were assessed in the liver." (PMID 39133714, 2024). "In addition, Oxymatrine significantly increased Sirt1 expression and AMPKα phosphorylation in the liver of rats with steatosis, which activating the Sirt1/AMPK signaling pathway." (PMID 37600712, 2023). "MEG3 reduction may also lead to liver inflammation and steatosis through the miR-34a/Nrf2 and miR-34a/SIRT1 signaling axes." (PMID 36742142, 2023). "Therefore, steatosis in rats exposed to dust and undergone IR injury was a consequence of down-regulating the expression of SIRT1." (PMID 36742142, 2023). "Moreover, CR ameliorated hepatocyte steatosis, attenuated white adipogenesis, and increased energy expenditure and expressions of SIRT1, PGC-1α, and phosphorylated AMPK in subcutaneous WAT and the hepatic tissues." (PMID 35721807, 2022). "Role of neutrophilic NCF1/SIRT1/AMPK in alcohol-induced steatosis in AH." (PMID 35838051, 2022). "Notably, previous studies have shown that hepatocyte-specific deletion of histone deacetylase Hdac3 and Sirt1 leads to steatosis." (PMID 33376138, 2021). "Furthermore, melatonin and berberine effects on autophagy activation and reduced steatosis were also observed to be SIRT1-dependent in mice under HFD with intact leptin signaling, as confirmed in liver-specific knockouts." (PMID 33937257, 2021). "To understand the mechanism underlying the protective effects of fucoidan against ethanol-induced liver injury and steatosis, we analyzed the hepatic expression of p-AMPKα, SIRT1, ChREBP, PGC-1α, and HNF-1α, which regulate hepatic fat metabolism and inflammatory response." (PMID 33994911, 2021). "However, SIRT1 was recently targeted by anti-steatosis and anti-inflammation treatments, and HSP70 has been implicated in both inflammation and fibrosis." (PMID 31315223, 2019). "In summary, this study found that miR-122 could repress the LKB1/AMPK signalling pathway via directly downregulating Sirt1, which then induced steatosis and lipogenesis in NAFLD." (PMID 31195981, 2019). "To evaluate whether SIRT1 activation is involved in GN-mediated protection against hepatic steatosis, inflammation, and oxidative stress, we further evaluated the effects of GN on SIRT1-AMPK signaling in the liver of ethanol-fed mice." (PMID 30200508, 2018).
steatosis (continued). "Thus, we found that the protective effects of LBP against steatosis were partly through the up-regulation of the SIRT1/AMPK pathway." (PMID 27824080, 2016). "Moreover, SIRT1 liver inhibition in rodents has been shown to induce an increase in de novo lipogenesis, leading to hepatic steatosis." (PMID 26890260, 2016). "Based on our previous study, we hypothesized that SalB exerted its “anti-steatosis” and “anti-inflammatory” effects by up-regulation of SIRT1." (PMID 26525891, 2015). "Our results have revealed that Res may reduce steatosis via enhanced Sirt1 expression and increased AMPK phosphorylation." (PMID 25140191, 2014). "In our study, increased expression of Sirt1 protein after the Res diet suggested that Res-induced Sirt1 activation may reduce steatosis, although mechanistically how Res activated Sirt1 remained unclear." (PMID 25140191, 2014). "In addition, activation of the Sirt1-forkhead box O1 (FOXO1) signaling pathway by resveratrol inhibits the expression of SREBP-1 in a cell model of steatosis induced by palmitate." (PMID 22363635, 2012). "Furthermore, SIRT1 overexpression reversed the effects of miR-181b on steatosis." (PMID 38370005, 2024). "Recently, we discovered the protective function of myeloid SIRT1 and its negative regulation of canonical inflammasome-pyroptosis in human and murine OLT, while others have shown that hepatocyte SIRT1 deficiency impaired lipid homeostasis and promoted steatosis in mouse livers under high-fat diet." (PMID 37996424, 2023). "Furthermore, our data have provided the novel evidence that OMT activates hepatic Sirt1/AMPK signaling which might be the potential therapeutic target of OMT for improving steatosis." (PMID 32210812, 2020). "Of particular interest in this respect, PHH with FFA-induced steatosis displayed a decrease in the expression of the genes encoding microtubule associated proteins 1A/1B light chain 3 beta (LC3; also known as MAP1LC3B) and sirtuin-1 (SIRT1), two markers of autophagy activation." (PMID 32094147, 2020). "Therefore, we think miR-34a-mediated PPARα regulation and SIRT1-AMPK pathway may be two separate regulatory mechanisms in steatosis, but there was a certain link between them, beacause both of them stimulated AMPK signaling." (PMID 26330104, 2015). "However, liver specific deletion of SIRT1 promotes hepatic steatosis." (PMID 24837835, 2014). "In mouse studies, ablation of SIRT1 in the liver or global SIRT7 deletion led to fatty liver under standard diet conditions, and global SIRT3 ablation accelerated steatosis development under HFD." (PMID 35743232, 2022). "Consistent with the attenuation of hepatic steatosis phenotype, our in vitro assays further demonstrated a slight, but significant, decrease in deacetylation levels of PLZF in hepatic SIRT1 knockout mice." (PMID 36438786, 2022). "In summary, our study provides strong evidence for the first time that Cim intervention prevents lipotoxicity-induced cell death and steatosis in hepatocytes via inhibiting TLR4/p38 overactivation and SIRT1 reduction." (PMID 35355867, 2022). "In AFLD mice, hepatic deletion of SIRT1 promotes steatosis and inflammation, aggravating disease.We demonstrated that BP reduced hepatocyte apoptosis in AFLD mice via SIRT1 pathways." (PMID 33971886, 2021). "In conclusion, this study revealed that fucoidan inhibited alcohol-induced steatosis and disorders of bile acid metabolism via the AMPK/SIRT1 pathway and the gut microbiota–bile acid–liver axis." (PMID 33994911, 2021). "The data from several laboratories suggested the role of the AMPK/SIRT1 signaling pathway in regulation of SREBP1 and lipogenic genes in the progression of ethanol-induced steatosis." (PMID 34836410, 2021). "The results suggested that fucoidan inhibited alcohol-induced steatosis, inflammation and oxidative stress through the AMPK/SIRT1 signaling pathway, and improved the disorder of bile acid metabolism by regulating gut microbiota-bile acid-liver axis." (PMID 33994911, 2021).
steatosis (continued). "Sirt1 levels are reduced in a HFD-induced NAFLD rodent model and are significantly lower in obese patients with severe steatosis." (PMID 33193730, 2020). "Although SIRT1 and HSP70 levels were previously reported to be decreased in rat livers with steatosis, inflammation, and fibrosis, SIRT1 and HSP70 levels were not lower in the HFCS group than in the control group." (PMID 31315223, 2019). "The current study indicated that oral melatonin (10 mg/kg), by influencing miR-34a/SIRT1/SREBP1 expression, ameliorated steatosis, ER stress, mitochondrial health and autophagy in high-fat diet-induced NAFLD in WT but not in HET mice." (PMID 31500354, 2019). "Reduced levels of SIRT1 have been reported in patients with ALD and hepatic depletion of Sirt1 in mice promotes steatosis, inflammation, and fibrosis in response to ethanol challenge." (PMID 30513996, 2018). "For example, Sirt-1 is involved in NAFLD and steatosis development in humans and mice, where SIRT increase counteracts the fatty liver phenotype." (PMID 29587401, 2018). "In a hepatocyte steatosis model, RGZ significantly reduced lipid accumulation and activated the Sirt1/6-LKB1-AMPK pathway." (PMID 25133775, 2014). "In a hepatocyte steatosis model with PA treatment, the regulatory effects of RGZ on Sirt1 were significantly blunted by Sirt6 knockdown, which suggests that up-regulation of Sirt1 by RGZ was partially dependent on Sirt6." (PMID 25133775, 2014). "Sirt1/6 knockdown aggravated hepatocyte fat accumulation as shown by increased TG content and suppressed the favorable effects of RGZ on hepatocyte steatosis." (PMID 25133775, 2014). "Here we show that RGZ alters hepatic Sirt1 in a rodent model of NAFLD and improves hepatocyte steatosis accompanied by elevations in adiponectin, Sirt1/6, and their downstream targets as well as AMPK phosphorylation in vitro." (PMID 25133775, 2014). "The longevity-related SIRT1 may improve MASLD by regulating ROS, PGC-1α, FoxO1/3, and AMPK to restore mitochondrial function and reduce steatosis of the liver." (PMID 39264516, 2024). "However, the inhibition of SIRT1 or AMPK significantly diminished these effects and attenuated the improvement of SNN on FFA-induced steatosis of the hepatocytes." (PMID 35945571, 2022). "SIRT1, a NAD-dependent histone deacetylase, plays a vital role in hepatic steatosis and inflammation, along with active participation in other cellular events like metabolism, inflammatory response, cell aging, and apoptosis through a variety of signaling pathways." (PMID 35368864, 2022). "Although the beneficial effects of caloric restriction are largely attributed to SIRT1 activation, resveratrol can modulate the activity of other sirtuins, making it possible that SIRT2 activation may improve steatosis through an ER stress-dependent pathway." (PMID 35743232, 2022). "SIRT1 levels remained unchanged in BAT and in the liver, which developed steatosis." (PMID 36555502, 2022). "SIRT1 may improve NAFLD by regulating ROS, PGC-1α, SREBP-1c, FoxO1/3, STAT3, and AMPK to restore mitochondrial function and reduce steatosis of the liver." (PMID 36008973, 2022). "In contrast, SIRT1-independent, NAMPT-upregulated processes included neutrophil chemotaxis and complement pathway concepts, whereas NAMPT suppressed de novo lipogenesis, hepatic steatosis, adipogenesis and retinoic acid pathways independent of SIRT1." (PMID 35228549, 2022). "Inhibition of miR-34a could alleviate steatosis and suppress lipid accumulation in the mouse NAFLD model by specifically targeting hepatic PPARα and SIRT1." (PMID 35052597, 2021). "Accordingly, the liver might promote steatosis by enhancing HIF-1α and inhibiting SIRT1 signaling that stimulates hepatosteatosis in ob/ob mice, and these phenomena were neutralized by losartan." (PMID 34360607, 2021). "Despite the suppression of lipogenic markers, SIRT1 overexpression in dams or sires did not significantly improve hepatic morphology or lower steatosis in MHF offspring." (PMID 33027895, 2020).